USP7 (ubiquitin specific peptidase 7)
Diseases named in the same sentence as USP7 in open-access papers (continued):
Sharing a sentence is not in itself a finding about the gene and the disease.
infection (continued). "In addition, ICP0 has been reported to rely on host protein USP7 to protect itself from autoubiquitination while remaining active to target additional substrates during productive infection." (PMID 36769256, 2023). "To determine the role of USP7 in the context of HAdV-C5 infection, we analyzed whether the viral DBP is ubiquitinated." (PMID 35254132, 2022). "The SUMO2-mediated degradation of USP7 observed under the ectopic expression of EBNA1 in HEK293 cells, but not when LCL cells express endogenous levels of EBNA1, suggesting that USP7 could be a key balance molecule to establish latency from primary infection." (PMID 32176739, 2020). "This clearly supports the notion that USP7 may exert its effects not only during early, but also at late times of infection." (PMID 23555268, 2013). "However, the specific effects of both approaches (knockdown and inhibition) upon other viral proteins such as E1B-55K or structural proteins clearly suggest that USP7 functions are necessary during the whole course of infection." (PMID 23555268, 2013). "Nevertheless, USP7 redistribution in the nucleus forming ring-like structures as seen in categories 5, 6 and 7 was observed in the majority of patterns analyzed up to 24 hours post infection." (PMID 23555268, 2013). "Interestingly, as infection proceeds USP7 colocalization with E1B-55K increasingly correlates with these ring-like structures (merge)." (PMID 23555268, 2013). "This may suggest that functional inhibition of USP7 cannot overcome the likely high transcription-translation activity at this stage of infection (at least for the early protein E1B-55K)." (PMID 23555268, 2013). "Our results clearly indicate that adenoviral progeny virions can be reduced in a significant manner (up to over 90%) even after an established infection using an inhibitor of USP7, results that could, at least qualitatively, also be confirmed with RNAi experiments." (PMID 23555268, 2013). "Based on the mass spectrometric analysis, the THP-1 macrophages infected with Y. enterocolitica for 2 hours post-infection (hpi) had an increased level of USP4 and USP7 but decreased level of OTUD6B." (PMID 37026055, 2023). "While the nuclear distribution of USP7 was observed to be diffuse in UBM2 mutant H5pm4250-infected cells at 24 h postinfection (hpi), it was comparable to WT infections at the later time point (48 hpi)." (PMID 35254132, 2022). "Cultures that showed near-complete infection as measured by GFP expression were cultured for 3–5 days and evaluated for expression of USP7 and DNMT1 by immunoblot." (PMID 29482658, 2018). "Prior to investigating whether infection led to ZIKV-derived HLA immunopeptide presentation by USP7-ATRT cells, we first sought to understand what HLA allotypes USP7-ATRT cells express and what peptides these HLA molecules present." (PMID 41166287, 2025). "72-hours after the infection, the investigators observed cell death and/or growth reduction in all the CNS tumor lineages, although infection of DAOY was less pronounced when compared to USP13-MED and USP7-ATRT." (PMID 39347716, 2024). "During infection, DBP-marked replication centers recruit the cellular deubiquitinase USP7." (PMID 36095031, 2022). "Performing ProcartaPlex ELISA assays, we assessed whether the soluble TNF factors of these pathways (TNF-alpha, TNFSF9 and TNFRSF9) were secreted following infection and observed significantly increased secretion of TNF-alpha and TNFRSF9 from both USP7 and USP13 cells at 48 hpi." (PMID 40240536, 2025). "Cells with tagged USP7 were infected with replicative, ANCHOR3-negative viruses to provide E1A expression in trans and an excess of ANCHOR3-GFP-positive vectors with E1 deleted at two different multiplicities of infection (MOI) and imaged for 24 h at 20-min interval between frames." (PMID 29997215, 2018).
infection (continued). "Regarding DUB expression, no apparent differences were found throughout infection in the levels of HAUSP, also called USP7, UCHL1, A20, USP10, STAMBP, and CYLD." (PMID 36851696, 2023). "Expression and steady-state levels of all analyzed cellular proteins (β-actin, USP7, Daxx, Rad50, Nbs1, Mre11, and PML) were not altered in UBM2 H5pm4250 versus WT H5pg4100 infection." (PMID 35254132, 2022). "However, the initial step of USP7 redistribution is probably independent of E1B-55K, since USP7 relocalization could be observed before detection of E1B-55K, and in the absence of colocalization and during infection with a virus lacking all E1B functions." (PMID 23555268, 2013). "In summary, it was possible to establish two USP7 knockdown cell lines with corresponding control cells, and find suitable conditions for HBX treatment in infection experiments where cell growth and viability were not significantly affected." (PMID 23555268, 2013). "First data in a proteome analysis from S. aureus infected macrophage-like cell line THP1 showed a decrease in the abundance of the analyzed proteins USP7, USP48, UCHL3, OTUD7B, and SENP1 (data not shown) which might indicate an intracellular role of Spls during infection." (PMID 39985644, 2025).
neurodevelopmental disorder (15 papers, 2018 to 2025). A behavioral and cognitive disorder with onset during the developmental period that involves impaired or aberrant development of intellectual, motor, or social functions. "This integrated approach holds promise for other neurodevelopmental disorders (such as USP7), enabling the simultaneous detection of pathogenic variants and the associated methylation signature." (PMID 41555921, 2025). "This partially encompasses the GRIN2A and USP7 genes associated with neurodevelopmental disorders, including autistic features." (PMID 38539661, 2024). "Likewise, the transcriptional activator AUTS2, KCNH7 potassium channel variants, lysine methyltransferase SETD2 (which is also downregulated in mice), and USP7, among others, are induced by rest, and their mutations are associated with a variety of neurodevelopmental disorders." (PMID 40725218, 2025). "Understanding these relationships is pivotal in advancing our understanding of USP7’s role in neurodevelopmental disorders, laying the groundwork for future development of targeted treatments and improving patient outcomes." (PMID 40166258, 2025). "The patient was a 15-year-old female patient with a complex neurodevelopmental disorder involving both cognitive and neurologic areas in which whole exome sequencing diagnosed a large de novo heterozygous deletions affecting USP7." (PMID 37679850, 2023). "By studying these models, we can understand how altered USP7 and TRIP12 activity influences chromatin remodeling and DNA methylation, crucial for neurodevelopmental disorders and providing insights into disease mechanisms and potential therapeutic targets." (PMID 39135741, 2024).
adenocarcinoma (7 papers, 2015 to 2025). A common cancer characterized by the presence of malignant glandular cells. "Conversely, it was also reported that USP7 is negatively associated with the prognosis of adenocarcinomas of non-small lung cancer (NSCLC) and the progression of the human colorectal xenograft model." (PMID 34580281, 2021). "According to the association analysis for EGFR mutation in patients with adenocarcinoma (n = 108, EGFR mutant = 64), we found 159 suggestive DMPs and six significant DMPs (cg09245319, cg17183999 [USP7], cg06366994 [CPE], cg24992236 [MEG9], cg22144719, and cg22448179 [EGFR])." (PMID 31450665, 2019). "Then, the prognostic role of USP7 was analyzed in 110 NSCLC samples (excluding the adenocarcinoma)." (PMID 25519684, 2015). "The USP7 expression was examined in NSCLC tumors (excluding adenocarcinoma), their corresponding non-tumorous tissues, and NSCLC cells." (PMID 25519684, 2015). "To investigate the USP7 expression in NSCLC tissues, we first detected USP7 expression in 12 pairs of fresh primary NSCLC tumors (excluding the adenocarcinoma tissues) and their corresponding non-tumorous tissues by qRT-PCR and Western blot analysis." (PMID 25519684, 2015). "Here, we found USP7 expressed high in NSCLC tissues (excluding the adenocarcinoma tissues) compared with adjacent non-tumorous tissues." (PMID 25519684, 2015).
hematological malignancies (6 papers, 2020 to 2026). "Our findings position USP7 inhibition as a double-edged sword in oncology and nominate PU.1 stabilization as a strategy to counteract stem cell exhaustion in aging and hematologic disorders." (PMID 41522346, 2026). "The role of USP7 is well-described in some types of onco-hematologic diseases." (PMID 37373211, 2023). "Therefore, the impact of USP7 on the pathogenesis of onco-hematological diseases, especially MDS, remains unclear." (PMID 37373211, 2023). "In recent years, some DUBs, such as USP7, USP9X and USP10, have been identified as promising therapeutic targets in hematological malignancies." (PMID 34454635, 2021).
breast (3 papers, 2017 to 2022). "Moreover,targeting USP7 with small molecule inhibitors (XL177A and P5091) selectivelyinhibited the growth of mutant APC-colorectal cancercells which are characterized by enhanced nuclear β-cateninaccumulation but not wildtype APC epithelial colorectalcells." (PMID 36589880, 2022).
CNS tumor (3 papers, 2019 to 2024). "The two embryonal CNS tumor cell lines, USP7 and USP13, formed the largest and most numerous tumoroids, while the GBM cell line U343-MG generated fewer and denser structures." (PMID 39599878, 2024). "Next, an in vivo study was conducted with a intracerebroventricular injection of ZIKV in BALB/c nude mice after period of CNS tumor establishment (1 to 2 weeks for DAOY, USP13-MED and USP7-ATRT cell lines)." (PMID 39347716, 2024). "The therapeutic potential of miR‐367 was further confirmed in vivo, in an orthotopic xenograft model of aggressive embryonal CNS tumors initiated by OCT4A‐overexpressing cells (Daoy, USP13‐MED, or USP7‐ATRT) in Balb/C nude mice." (PMID 31402560, 2019).
bone disorder (1 paper, 2025). "Targeting the CK2/USP7/RUNX2 axis presents a potential therapeutic strategy for managing CKD-related bone disorders." (PMID 40447997, 2025).
cardiovascular disease (1 paper, 2022).
genetic disease (1 paper, 2022). "It is a dominant genetic disease caused by USP7 gene (*602519) mutations on chromosome 16p13.2." (PMID 36466803, 2022).
USP7 also shares sentences with these, for which no sentence is quoted: epilepsy (3 papers); hepatoblastoma (3); neurodegenerative disease (3); T-cell acute lymphoblastic leukemia (3); Epileptic encephalopathy (2); gastroesophageal reflux (2); metabolic disorders (2); neurological disorders (2); prostate adenocarcinoma (2); schizophrenia (2); T cell lymphoma (2); acute pancreatitis (1); Alzheimer disease (1); Arthritis (1); asthma (1); ataxia telangiectasia (1); attention deficit-hyperactivity disorder (1); autoimmune disorders (1); behavioral disorders (1); benign melanocytic skin nevus (1); bladder tumor (1); bronchiectasis (1); carcinoids (1); cervical squamous cell carcinoma (1); cholelithiasis (1); clear cell renal cell carcinoma (1); cocaine use disorder (1); colorectal adenocarcinoma (1); colorectal tumor (1); cutaneous melanoma (1).
A further 38 diseases each share a sentence with USP7 in 1 paper.